EXTL1 (exostosin like glycosyltransferase 1)
Description:
Glycosyltransferase required for the biosynthesis of heparan-sulfate (HS). Transfers N-acetyl-alpha-D-glucosamine to the nascent HS chain (GlcNAcT-II activity). Appears to lack GlcNAcT I and GlcAT-II activities.
Synonyms: EXTL; MGC70794
Tractability: Antibody: UniProt predicts a signal peptide or a membrane-spanning region.
Gene: Protein-coding gene on chromosome 1 (26,019,884 to 26,036,464, forward strand). Ensembl gene ENSG00000158008.
Subcellular location: Endoplasmic reticulum membrane
Subcellular location (Human Protein Atlas): Basal body; Centrosome
Pathways (Reactome):
Cellular responses to stimuli: XBP1(S) activates chaperone genes
Gene Ontology:
Molecular function: glucuronosyl-N-acetylglucosaminyl-proteoglycan 4-alpha-N-acetylglucosaminyltransferase activity; protein binding; acetylglucosaminyltransferase activity; glucuronosyltransferase activity; glycosyltransferase activity
Biological process: heparan sulfate proteoglycan biosynthetic process; skeletal system development; glycoprotein biosynthetic process
Cellular component: endoplasmic reticulum membrane; Golgi apparatus; membrane
Genetic constraint (gnomAD): Loss-of-function variants: 43 observed, 59.08 expected, observed/expected ratio (o/e) 0.73, 90% interval 0.57 to 0.94. The upper end of that interval is the gene's LOEUF score, 0.94, which puts it in group 3 of 6, group 1 being the genes least tolerant of losing a copy. Missense variants: 760 observed, 866.85 expected, observed/expected ratio (o/e) 0.88, 90% interval 0.82 to 0.93. Synonymous variants: 352 observed, 361.05 expected, observed/expected ratio (o/e) 0.97, 90% interval 0.89 to 1.07.
Homologues: Orthologues: chimpanzee EXTL1 (99% identical), macaque EXTL1 (91% identical), pig EXTL1 (81% identical), dog EXTL1 (80% identical), guinea pig EXTL1 (79% identical), rabbit EXTL1 (78% identical), mouse Extl1 (74% identical), rat Extl1 (74% identical), Drosophila melanogaster ttv (40% identical), Caenorhabditis elegans rib-1 (17% identical), zebrafish ext1c (12% identical). Paralogues in human: EXT1 (47% identical), EXT2 (28% identical), EXTL3 (27% identical), EXTL2 (12% identical).
Diseases named in the same sentence as EXTL1 in open-access papers:
EXTL1 is named in the same sentence as 16 diseases in open-access papers, as found by Europe PMC text mining. Sharing a sentence is not in itself a finding about the gene and the disease. The quoted sentences say what the papers report.
glioma (2 papers, 2023 to 2026). A benign or malignant brain and spinal cord tumor that arises from glial cells (astrocytes, oligodendrocytes, ependymal cells). "To identify glycosyltransferases relevant to gliomas, we conducted a pan-cancer analysis of EXT family genes (EXT1, EXT2, and EXTL1-3) using harmonized TCGA and GTEx transcriptomic datasets." (PMID 41438585, 2026). "However, EXTL1, ST8SIA3, and GALNT9 demonstrated a negative relation with oncogenic pathways, suggesting a potentially protective role for glioma progression." (PMID 37663248, 2023).
neuroblastoma (2 papers, 2018 to 2025). Neuroblastoma (NB) is the most common solid, extracranial childhood tumor. "Extl1 is a putative tumor-suppressor gene found in neuroblastoma patients." (PMID 29566670, 2018). "Exostosin-like glycosyltransferase 1 (EXTL1), a member of the EXT family of tumor suppressor genes, was identified as a candidate neuroblastoma tumor-suppressor gene." (PMID 40660393, 2025).
COVID-19 (1 paper, 2025). A disease caused by infection with severe acute respiratory syndrome coronavirus 2. "Among the 5 common DEGs, four were significantly downregulated (ERP27, SYTL5, EXTL1, DIO2) and one was upregulated (STXBP6) in the COVID-19 dataset." (PMID 40660393, 2025).
exostoses (1 paper, 2020). "Considering that dominant mutations in EXT1 and EXT2 genes cause hereditary multiple exostoses and the EXTL1 gene is expressed at very low levels in brain cells, EXTL2 and EXTL3 represent the most promising candidates in this pathway for SRT." (PMID 32121121, 2020).
liver cancer (1 paper, 2018). An epithelial or non-epithelial malignant neoplasm that arises from the liver. "To determine whether DNA methylation alterations in the DMRs of Mst1r, Slpi, and Extl1 are involved in the expression of these genes, we assessed the effects of the DNA methylation inhibitor 5-aza-dC on the DNA methylation statuses and gene expressions in mouse liver cancer cell lines." (PMID 29566670, 2018).
pterygium (1 paper, 2025). A wedge-shaped fibrovascular lesion arising from the bulbar conjunctiva and extending to the cornea. "A similar tendency was observed in pterygium tissues versus normal controls, with a significant decrease in the level of four genes (ERP27, SYTL5, EXTL1, DIO2) and an increment of gene STXBP6." (PMID 40660393, 2025).
cancer (3 papers, 2018 to 2026). A tumor composed of atypical neoplastic, often pleomorphic cells that invade other tissues. "Conversely, EXTL1, EXTL2, and EXTL3 showed inconsistent and context-specific expression patterns across cancers." (PMID 41438585, 2026).
tumor (3 papers, 2018 to 2025). "We also measured gene expression levels of the normal and tumor tissues by real-time PCR and confirmed up-regulation of Mst1r and Slpi and down-regulation of Extl1 in the tumor tissues." (PMID 29566670, 2018).
infection (1 paper, 2025). The state of being infected such as from the introduction of a foreign agent such as serum, vaccine, antigenic substance or organism. "Required for the biosynthesis of heparan sulfate, EXTL1 is involved in DC-mediated Th1 and Th17 development in the immune response against infection." (PMID 40660393, 2025).
EXTL1 also shares sentences with these, for which no sentence is quoted: breast carcinoma (1 paper); gastric cancer (1); immune deficiency (1); Insulin resistance (1); leukemia (1); Obesity (1); rectal cancer (1).